FGF21 (fibroblast growth factor 21)
Diseases named in the same sentence as FGF21 in open-access papers (continued):
Sharing a sentence is not in itself a finding about the gene and the disease.
Obesity (continued). "Dubosiella has been shown to ameliorate obesity, specifically regulated by FGF21, significantly improving liver function and reducing lipid accumulation in mice with NAFLD." (PMID 39606109, 2024). "Autophagy-deficient mouse muscle cells or those with mitochondrial dysfunction can reduce fat production by secreting FGF21, thereby preventing obesity and insulin resistance." (PMID 38902808, 2024). "Results from prior investigations have demonstrated that FGF21 is significantly elevated in individuals diagnosed with obesity, insulin resistance, T2DM, dyslipidemia and non-alcoholic fatty liver disease." (PMID 39597026, 2024). "On the other hand, the age-associated increase in FGF21 levels is reminiscent of that occurring in obesity, suggesting that aging may be associated with a progressive loss of FGF21 responsiveness in tissues, giving rise to a reactive FGF21 up-regulation in a so-called “FGF21 resistance” scenario." (PMID 37914970, 2024). "FGF21 is a pleiotropic metabolic hormone primarily secreted by the liver, which is a promising therapeutic agent for obesity, type 2 diabetes and non-alcoholic steatohepatitis." (PMID 38409275, 2024). "FGF21 exerts anti-obesity, anti-diabetic, and anti-inflammatory effects by enhancing lipid and glucose metabolism." (PMID 39335642, 2024). "Understanding the relationship between increased FGF21 concentration and increased mortality will help develop effective FGF21-based pharmacotherapy targeting obesity, diabetes and other metabolic disorders." (PMID 39302236, 2024). "Specifically, higher serum FGF21 concentrations have been described in humans with obesity and diabetes, suggesting the potential presence of FGF21 resistance in addition to insulin resistance." (PMID 38957656, 2024). "FGF21 analogs have been shown to increase adiponectin levels in non-human primates and humans with metabolic diseases such as T2D, obesity, and NASH." (PMID 39409124, 2024). "Brown adipocytes are potential therapeutic targets for obesity-related metabolic diseases and stimulate FGF21 expression by regulating the molecular clock brain and muscle Arnt-like 1 in brown adipocytes." (PMID 38957396, 2024). "LY2405319 is another engineered FGF21 protein that is proven to be effective in a randomized clinical trial in obesity and type 2 diabetes patients, such as reducing body weight, fasting triglycerides, and insulin levels." (PMID 38292187, 2024). "Studies involving exercise T programs have reported decreased plasma/serum FGF21 levels in individuals with obesity due to attenuated FGF21 resistance." (PMID 39640300, 2024). "Transgenic overexpression and pharmacological administration of FGF21 under obesogenic conditions has been shown to protect animals from diet-induced obesity and improved systemic glucose homeostasis." (PMID 39680603, 2024). "For example, FGF21 analogs and agonists of FGFR1/KLB receptor complexes have displayed therapeutic potential in improving obesity and its associated complications." (PMID 39872218, 2024). "Several studies have demonstrated therapeutic benefits of FGF21 for obesity-related metabolic disorders, including the reduction in adiposity and improvement in insulin resistance, NAFLD, among others." (PMID 38981607, 2024). "In the clinical setting, FGF21 levels are elevated in a range of human diseases, including obesity, non-alcoholic fatty liver disease, diabetes mellitus, chronic kidney disease, atherosclerosis, and coronary heart disease." (PMID 39194718, 2024). "The phenotypes observed in both the C-WD and I-WD mice, characterized by obesity development, steatosis, and liver alterations, were also found in FGF21 knockout mice." (PMID 38474774, 2024). "FGF21 was proven to increase both in the liver of patients suffering from steatosis and mouse models of obesity or NAFLD where ER stress was triggered." (PMID 38292187, 2024).
Obesity (continued). "Assess the relations between serum FGF-21 and Visfatin with obesity and its metabolic disorders, and their use as potential predictors for metabolic risk factors in a sample of Egyptian obese children." (PMID 38216702, 2024). "Recent discoveries highlight FGF21 as a key regulator of metabolic homeostasis with a potent anti-obesity effect (Lu, Li & Luo, 2021)." (PMID 38304193, 2024). "Huge numbers of studies have revealed that FGF21 treatment can alleviate many age-related metabolic disorders and exhibit anti-inflammatory property in multiple diseases like obesity, bacterial infection and neurodegeneration." (PMID 38653921, 2024). "It has been proposed that elevated serum FGF21 levels in individuals with obesity and rodents result from FGF21 resistance in adipose tissues due to reduced expression of its receptor complex." (PMID 38321233, 2024). "Our results found that after high-fat feeding, the expression of FGF-21 in the liver and skeletal muscle of obesity mice was compensatory increased compared to normal mice." (PMID 38732501, 2024). "Clinically, elevated circulating levels of FGF21 have been observed in several dysmetabolic conditions, including obesity, insulin resistance, and T2D." (PMID 39409124, 2024). "It was reported that obesity reduces sensitivity to FGF21, resulting in increased levels of circulating FGF21 at rest, which is considered a state of FGF21 resistance." (PMID 39354624, 2024). "SPARC has recently attracted substantial interest due to its roles in obesity, insulin resistance, and metabolic syndrome, and FGF21 is thought to have therapeutic potential for obesity, T2DM, and NAFLD." (PMID 39391493, 2024). "Another tissue that can be targeted as an anti-obesity approach is the skeletal muscle since this tissue secretes several myokines such as irisin and FGF21 that participate in lipid metabolism." (PMID 38731880, 2024). "Taken together, our research results reveal that the liver and skeletal muscles of obesity-resistant mice exhibit reduced ectopic lipid deposition with the joint participation of FGF-21 and perilipin." (PMID 38732501, 2024). "In animal studies, it was also found that the administration of FGF21 to mice with high-fat diet-induced obesity reduces their body weight by increasing energy expenditure and reducing glycemia, and leads to the reduction of hepatic steatosis." (PMID 39064306, 2024). "This study underscores the promise of FGF21-based gene therapy for the treatment of obesity, insulin resistance, and various types of diabetes mellitus (DM2)." (PMID 39902162, 2024). "In mouse models of obesity, FGF21 reduces plasma glucose and triglycerides and promotes weight loss; furthermore, FGF21 overexpression results in resistance to weight gain in mice on high-fat diets." (PMID 39452947, 2024). "In summary, this study found that ectopic lipid deposition in the liver and skeletal muscles of obesity-resistant mice was reduced, with a significant increase in FGF-21 expression." (PMID 38732501, 2024). "In this study, we found that ectopic lipid deposition in the liver and skeletal muscles of obesity-resistant mice exhibited a reduced and significant increase in FGF-21 expression." (PMID 38732501, 2024). "Recent studies suggest that FGF21 treatment can mitigate various age-related metabolic disorders, including atherosclerosis, obesity, T2DM, and cardiovascular diseases." (PMID 39100807, 2024). "FGF-21 and Visfatin are related to the obesity markers, but they cannot be used as potential predictors for metabolic disturbance in obese prepubertal children; both had insignificant correlations with the metabolic risk factors." (PMID 38216702, 2024). "Elevated FGF21 levels in conditions like metabolic syndrome, obesity, insulin resistance, diabetes, and hypertension suggest a response to poor metabolic status." (PMID 39687000, 2024).
Obesity (continued). "This study aimed to assess the levels of fibroblast growth factor 21 (FGF21) in subjects with obesity after gastric sleeve surgery and explore its correlation with lipid and glycemic parameters." (PMID 39100807, 2024). "It is important to note that the concentrations of FGF21 administrated in our study were intended to mimic levels observed in HFD-induced NAFLD or obesity." (PMID 38238320, 2024). "FGF21 is the master metabolic regulator in upregulation of energy expenditure and has promising therapeutic application for the treatment of obesity-related metabolic disorders." (PMID 38212382, 2024). "This study aims to investigate the effects of low-fat diet on liver enzymes and serum levels of inflammatory cytokines such as chemerin, IL-6, TNF-α, and myokines such as irisin, FGF-21 in individuals with overweight, obesity and NAFLD." (PMID 38608067, 2024). "DB-LNPs were used to deliver Cas9 mRNA/sgRNA for editing the TTR gene and mRNA encoding human fibroblast growth factor 21 (FGF21) to the liver as a strategy to treat the genetic disease transthyretin amyloidosis, and obesity and fatty liver, respectively." (PMID 39337651, 2024). "FGF21, a mitochondrial stress biomarker, is also elevated in obesity, type 2 diabetes, coronary heart disease, and chronic kidney disease." (PMID 39124668, 2024). "Overall, these findings have guided the design and development of several FGF21 analogs and mimetics that have shown promising therapeutic efficacy against obesity and T2D, demonstrating anti-inflammatory, antidiabetic, and hypolipidemic properties." (PMID 39409124, 2024). "Clinical trials have demonstrated the potential of recombinant FGF21 for the treatment of type 2 diabetes, obesity, and other comorbidities, but its physiological role in atherosclerosis (AS) has only gained attention in recent years." (PMID 39144082, 2024). "Elevated levels of circulating FGF21 are observed in various metabolic disorders, including DM, obesity, and cardiovascular disease." (PMID 38312833, 2024). "To date, research on FGF21 has focused primarily on its beneficial functions in metabolic disorders such as obesity, type 2 diabetes, and non-alcoholic- or metabolic dysfunction-associated steatohepatitis by reducing fat mass, hyperglycemia, and dyslipidemia." (PMID 39211324, 2024). "In Fgf21-KO mice, the role of endogenous FGF21 in improving obesity resistance, blood glucose control, and hepatic lipid homeostasis related to muscle mitochondrial stress can be negligible." (PMID 39872377, 2024). "Irisin and FGF21 act as adipokines beiging adipocytes that attenuate diet-induced obesity by stimulating thermogenesis and increase insulin sensitivity." (PMID 39267855, 2024). "Here, the authors show that the defence against overfeeding is preserved in obesity, and that it is independent from FGF21 and MC4R." (PMID 38331907, 2024). "In patients with obesity and T2D, treatment with long-acting FGF21 analogs resulted in significant improvements in body weight and circulating lipoprotein levels." (PMID 39409124, 2024). "Over recent years, several clinical trials of human FGF21 analogues have been conducted in subjects with type 2 diabetes mellitus, obesity and fatty liver." (PMID 39341924, 2024). "A weak but significant correlation was also observed for FGF-21, for which secretion and action in obesity are often disturbed." (PMID 37189422, 2023). "Previous studies have reported that administration of FGF21 and FGF21 analogs reduce bodyweight in animal models of obesity and in short‐term clinical trials." (PMID 37334756, 2023). "The administration of human or murine FGF21 alleviates the progression of NAFLD in HFD-induced obesity models." (PMID 36653390, 2023). "High FGF21 levels have been reported in various metabolic diseases, including obesity, fatty liver disease, and diabetes." (PMID 37818094, 2023).
Obesity (continued). "In accordance with our results, other authors observed higher serum FGF21 levels in subjects with obesity compared to those detected in lean individuals." (PMID 38137540, 2023). "LY2405319 (Eli Lilly and Company, Indianapolis, IN) is a modified human recombinant FGF21 analog engineered for increased stability and retained metabolic benefits and has been successfully used to treat obesity and hyperglycemia in rodent and primate models." (PMID 36756310, 2023). "FGF21 administration was shown to protect against neuroinflammation in oxidative stress, ischemic stroke, and in obesity." (PMID 36650549, 2023). "This is in line with previously published studies that showed FGF-21 was increased in obesity and NAFLD and that decreased soluble TWEAK levels are associated with increased risk of diabetes and metabolic syndrome." (PMID 37371624, 2023). "For instance, FGF21 analogs can be used in obesity before T2D develops to improve FGF21 responsiveness and maintain insulin sensitivity in the longer term." (PMID 36594101, 2023). "Fibroblast growth factor 21 (FGF21) is a peptide hormone involved in energy homeostasis that protects against the development of obesity and diabetes in animal models." (PMID 36028609, 2023). "Intracerebroventricular injection of FGF21 also increases sympathetic activity, insulin sensitivity, and energy expenditure in rat models of obesity." (PMID 36028609, 2023). "Physiologically, FGF21 is considered a stress-induced hormone whose levels rise in metabolically compromised states, such as obesity and NASH." (PMID 36648330, 2023). "A paradoxical situation, that illustrates the complexity of the FGF21 pathways, is that while its plasma levels increase during exercise, they also do so in processes of metabolic deregulation, such as obesity or liver diseases." (PMID 36909316, 2023). "While prolonged fasting increases the production and release of FGF21 to stimulate gluconeogenesis, a number of studies have shown that FGF21 administration in animals with obesity or diabetes effectively improves insulin sensitivity and glucose metabolism." (PMID 37049555, 2023). "Effect modification by overweight/obesity was significant in 3 of the proteins in the sex‐adjusted model: fibroblast growth factor 21 (FGF21), interleukin 4 (IL‐4), and uPA." (PMID 36973952, 2023). "Though FGF21 is promising as an anti-obesity agent, its relationship with obesity remains controversial." (PMID 37685184, 2023). "For example, the effect of FGF21 on glucose uptake by myotubes is similar to the effect of insulin, with upregulated FGF21 expression in skeletal muscle protecting against diet-induced obesity and insulin resistance." (PMID 37153220, 2023). "Described as anti-obesity and anti-diabetic, FGF-21 and its receptor agonists improve insulin sensitivity (IS) and promote weight loss by stimulating brown fat thermogenesis and increasing release of adiponectin serum levels." (PMID 37239098, 2023). "In mice, Fgf21 administration/overexpression is protective, preventing obesity in animals with diet-induced obesity, and improving hepatic triglyceride concentrations, cholesterol levels, energy expenditure and insulin sensitivity." (PMID 36923222, 2023). "Elevated levels, as proposed in obesity and evidenced by multiple animal studies, are likely, however, due to aberrant FGF21 signalling and an FGF21 resistant state." (PMID 36028609, 2023). "Subjects with obesity showed an altered serum cytokine profile, characterized by increased levels of leptin, FGF21 and NOV/CCN3, a decreased level of adiponectin, and similar levels of vaspin and chemerin compared to normal-weight subjects." (PMID 38137540, 2023). "As another genetically engineered variant of endogenous FGF-21, LLF580 was investigated in a double-blind multicentre trial in adults with obesity and hypertriglyceridemia." (PMID 37239098, 2023).
Obesity (continued). "In the context of obesity, pharmacological administration of FGF21 to obese rodents reverses diabetes and obesity through increasing energy expenditure." (PMID 37818094, 2023). "The functions of FGF21 have spurred several research groups to test the effects of treatment with FGF21 or developed analogs on models of metabolic diseases such as obesity and diabetes." (PMID 37948566, 2023). "Here, we review the current regulatory mechanisms of FGF21, summarize its role in obesity, diabetes, hyperlipidemia, and hypertension, and discuss the possibility of FGF21 as a potential target for the treatment of metabolic syndrome." (PMID 37576954, 2023). "FGF21 increases metabolic rates under baseline conditions but is dispensable for the resistance to diet-induced obesity (DIO) reported in OPA1 BKO mice." (PMID 37819027, 2023). "Except for causing obesity, OVX also causes hyperglycemia and raises the risk of insulin resistance and even diabetes in females, while liver-derived FGF21 is a pivotal factor to regulate both glucose metabolism and insulin sensitivity." (PMID 37834368, 2023). "The expression of massive DEGs (86%) in OVX mice was recovered back to the sham control levels after FGF21 LKO, strongly suggesting a pivotal role of liver-derived FGF21 in OVX-induced obesity." (PMID 37834368, 2023). "FGF21 resistance has previously been described in obesity, of which the mRNA level of FGF21 was observed higher in the white adipose and liver tissues of the obese mice." (PMID 37009852, 2023). "Mechanically, we found that FGF21 LKO reduced circulating insulin levels, thus causing the dissociation between decreased central obesity and the improvement of obesity-related metabolic syndromes in OVX mice." (PMID 37834368, 2023). "According to surface plasmon resonance (SPR) experiments, in vitro cell-based assays, and model high-fat diet (HFD)-induced obesity studies, heated FGF21 maintained biological activities that were comparable to those of non-heated and commercial FGF21s." (PMID 36653390, 2023). "Increasing FGF21 production prevented the mice from developing obesity while on the high fat diet by making the body burn more fat in the liver and brown fat tissue." (PMID 36648330, 2023). "Numerous clinical and basic studies have shown that FGF21 is involved in metabolic diseases such as diabetes, obesity, and nonalcoholic fatty liver disease." (PMID 37218012, 2023). "As FGF21 is known to reduce obesity and blood glucose levels by enhancing glucose homeostasis, further correlation analysis was performed." (PMID 37061742, 2023). "Fibroblast growth factor 21 (FGF21) has pharmaceutical potential against obesity-related metabolic disorders, including non-alcoholic fatty liver disease." (PMID 36653390, 2023). "FGF21 has potent antidiabetic and lipid-lowering effects in animal models of obesity and type 2 diabetes mellitus." (PMID 37049560, 2023). "By showing a protective role in lipid, glucose, and energy homeostasis, FGF-21 represents an extremely promising therapeutic target in the treatment of obesity and T2D." (PMID 37239098, 2023). "Paradoxically increased serum FGF21 level was found in patients with obesity and type 2 diabetes indicating a possible compensatory response to metabolic alterations." (PMID 36837889, 2023). "In particular, promising data revealed that fibroblast growth factor (FGF)-19, FGF-21 and leptin offer great potential for future clinical application in the treatment of obesity and related comorbidities." (PMID 37239098, 2023). "p38, which is a downstream molecule of FGF21, is activated in the livers of mouse models of obesity." (PMID 36742397, 2023). "Previous studies have shown significantly elevated levels of FGF21 in patients with type 2 diabetes, nonalcoholic fatty liver and obesity." (PMID 37218012, 2023). "KLB is decreased in WAT and BAT during DM in mice, indicating the impaired FGF21 thermogenic effect during DM and obesity." (PMID 36594101, 2023).